ALDH1A1 (aldehyde dehydrogenase 1 family member A1)
Diseases named in the same sentence as ALDH1A1 in open-access papers (continued):
Sharing a sentence is not in itself a finding about the gene and the disease.
alcoholism (15 papers, 2007 to 2025). "Aldehyde dehydrogenase 1 family member A1 (ALDH1A1) is involved in metabolic regulation and is known to be associated with alcohol dependence and androgen insensitivity syndrome." (PMID 40608007, 2025). "One study in Southwest California Indians found that people carrying an ALDH1A1*2 allele had lower rates of alcohol dependence and lower maximum number of drinks ever consumed in a 24-hour period." (PMID 17718394, 2007). "Among Afro-Trinidadians, however, the small number of subjects with atypical ALDH1A1 polymorphisms limited any conclusions on the possible impact on alcoholism in that population." (PMID 17718398, 2007). "A variant of the ALDH1 enzyme that is encoded by the ALDH1A1*2 allele, however, was found in a small proportion of a group of Southwest California Indians and had a protective effect against alcoholism in that population." (PMID 17718395, 2007). "ALDH1, which is encoded by the ALDH1A1 gene, has been associated with alcoholism, alcohol-induced flushing, and alcohol sensitivity." (PMID 17718396, 2007). "Third, the presence of at least one copy of a variant in the gene encoding for cytosolic ALDH1A (i.e. ALDH1A1*2) was found to be associated with an increase in alcohol dependence in Indo-Trinidadians." (PMID 17718398, 2007). "Thus, the mechanism underlying ALDH1A1-related alcoholism is different from the gene cluster of DRD2, DRD3, GRIN2B, and NTRK2, which is directly involved in behavioural rewarding effects of alcohol consumption." (PMID 28512340, 2017). "ALDH1A1 is associated with alcoholism as it confers protective effects against alcoholism caused by the deficiency of aldehyde dehydrogenase in aldehyde metabolism and results in an extremely high aldehyde level in the blood, thus causing aversive toxic and skin flushing responses in Caucasians41." (PMID 28512340, 2017). "However, researchers have found that another polymorphism, called ALDH1A1*2 in the ALDH1A1 gene, is associated with greater risk for alcoholism in African populations but not in Asian populations." (PMID 26259086, 2015). "However, a variant in the gene encoding cytosolic ALDH1A (i.e. ALDH1A1*1/*2) was found to be associated with an increase in alcohol dependence in Indo-Trinidadians." (PMID 17718398, 2007). "Two of these alleles that are found in African Americans—ALDH1A1*2 and ALDH1A1*3—may be associated with a reduced risk of alcoholism." (PMID 17718396, 2007). "Moreover, the results of that study suggested that the ALDH1A1*2 and ALDH1A1*3 alleles may be associated with a reduced risk of alcoholism." (PMID 17718396, 2007). "Similarly, the ALDH1A1*3 allele, which has been identified exclusively in African Americans, also may be associated with a reduced risk of alcoholism." (PMID 17718396, 2007). "Diethyldithiocarbamate (DE), the active metabolite of the FDA-approved anti-alcoholism drug disulfiram, irreversibly inhibits aldehyde dehydrogenase 1A1 (ALDH1A1)." (PMID 40733146, 2025). "Additionally, research has shown that ALDH1A1 can regulate the expression of NFATc1, a key regulator of osteoclast differentiation, and that disulfiram can act through the ALDH1A1‒NFATc1 axis as a treatment for alcohol-related osteoporosis." (PMID 40708788, 2025). "Importantly, we are the first to report SNPs associated with unequal age-of-onset distributions for susceptible cases to alcoholism [rs172677 on GRIN2B (p = 0.013), rs1439047 on NTRK2 (p = 0.005), rs63319 on ALDH1A1 (p = 0.033), and rs1079597 on DRD2 (p = 0.028)]." (PMID 28512340, 2017). "DSF re-purposing from its long-term clinical use against alcoholism to an anti-cancer drug is based on its ability to act as an ALDH1A1/ALDH2 inhibitor, a property not shared by other Cu chelators like TTM." (PMID 30792807, 2019).
squamous cell carcinoma (15 papers, 2008 to 2025). A carcinoma arising from squamous epithelial cells. "Here, we demonstrated that low proteasome activity in FaDu squamous cell carcinoma cells is positively associated with high ALDH activity and ALDH1A1 protein levels, indicating that proteasome-low CSCs overlap with the ALDH-high epithelial CSC phenotype." (PMID 40597978, 2025). "ALDH1A1 was identified as a novel CD8+ T-cell-defined tumor antigen in squamous cell carcinoma of the head and neck." (PMID 22110949, 2011). "Our previous study, using rabbit polyclonal antibody against human ALDH1A1 (ab63026, Abcam, Cambridge, UK) has proved that ALDH1 expression in vulvar squamous cell carcinomas predicted a significantly better survival than the ALDH1 negative cases." (PMID 26148881, 2015). "Other recent work in humans demonstrated ALDH3A1 and ALDH1A1 expression by immunohistochemistry in squamous cell carcinomas (SSCAs) and adenocarcinomas (AdenoCAs), but not in small cell lung cancer (SCLC)." (PMID 21489244, 2011). "Moreover, ALDH1A1 and ALDH3A1 exhibit elevated expression in squamous cell carcinoma and adenocarcinoma, and their upregulation may contribute to malignant transformation." (PMID 40868269, 2025).
diabetes (13 papers, 2010 to 2025). "The importance of fatty liver was particularly striking among the top 30 diabetes-associated proteins (e.g. HGF, IGSF3, IL1RA, ALDH1A1, HNMT, ERBB2 and CDCP1)." (PMID 33279861, 2021). "Taken together with our data on retinal aldehyde detoxification in diabetes, these findings suggest that hyperglycaemia downregulates retinal ALDH1A1 expression, leading to ACR/FDP-lysine accumulation within Müller cells and resulting in oxidative stress and inflammation." (PMID 30112688, 2018). "After menopause, the protection seems to weaken in females and the onset of diabetes induces changes in renal gene expression patterns, including those related to mitochondrial metabolism or FAO (Crot, Aldh1a1, Hmgcs2, Acadm)." (PMID 35230975, 2022).
metastatic tumors (13 papers, 2013 to 2024). "Altogether, these findings demonstrate an opposite association of ALDH1A1 and ALDH1A3 expression with PCa clinical outcomes and their differential expression in metastatic tumors." (PMID 38169509, 2024). "Regarding the specificity of these genes in metastatic tumors, the expression levels of ALDH1A1 and IGFBP1 were increased by 15.6% and 6.3%, respectively, compared with normal liver tissues, considering a contamination rate of <3%." (PMID 27152521, 2016). "Furthermore, ALDH1A1 expression was found more frequently in metastatic tumors than in primary tumor tissues, whereas stromal ALDH1A1 expression appeared more frequently in primary tumors than in metastatic tumors." (PMID 34572930, 2021).
acute myeloid leukemia (12 papers, 2012 to 2025). Acute myeloid leukemia (AML) is a group of neoplasms arising from precursor cells committed to the myeloid cell-line differentiation. "It is hence imperative that ALDH1A1 is methodically targeted, particularly for the acute myeloid leukemia patients of the poor prognosis risk group that overexpress ALDH1A1 RNA." (PMID 37298333, 2023). "It has been previously shown that the aldehyde dehydrogenase (ALDH) family member ALDH1A1 has a significant association with acute myeloid leukemia (AML) patient risk group classification and that AML cells lacking ALDH1A1 expression can be readily killed via chemotherapy." (PMID 37761947, 2023). "Not only is the gene ALDH1A1 on average significantly overexpressed in the poor prognosis group at the RNA level, but its protein product, ALDH1A1 protects acute myeloid leukemia cells from lipid peroxidation byproducts." (PMID 37298333, 2023). "Increased activity of ALDH1A1 has been observed in the stem cell populations of multiple myeloma, acute myeloid leukemia and malignant mammary cells." (PMID 23236365, 2012). "However, the role of ALDH1A1 in acute myeloid leukemia has been unclear in the past due to evidence that normal cells often have higher aldehyde dehydrogenase activity than leukemic cells." (PMID 37298333, 2023).
adenoma (12 papers, 2007 to 2023). A neoplasm arising from the epithelium. "Consistently, ALDH1A1 expression in colorectal adenoma is associated with a higher risk of metachronous adenoma independent of adenoma size or histopathology." (PMID 25788273, 2015). "Moreover, in low-grade colon adenomas, ALDH1A1 expression was higher than in higher grade adenomas." (PMID 36139578, 2022). "To this aim we studied the expression of LGR-5, MSI-1, DCAMKL-1, CD133 and ALDH1-A1 in normal mucosa, in MDF (microscopic precancerous lesions) and in macroscopic tumours (adenomas) of DMH-induced rats using immunohistochemistry." (PMID 23374535, 2013).
osteosarcoma (12 papers, 2012 to 2024). A usually aggressive malignant bone-forming mesenchymal neoplasm, predominantly affecting adolescents and young adults. "The PROM1 gene, also known as CD133+, is one of the principal markers of osteosarcoma cancer stem cells together with CD34, a marker of the undifferentiated state of the cells, and the ALDH1A1 genes." (PMID 27651797, 2016). "Similarly, in osteosarcoma cells, KLF4 suppression prevented sphere formation and attenuated the levels of many stem cell-related markers, including ALDH1A1." (PMID 34680284, 2021).
sarcoma (12 papers, 2012 to 2025). A usually aggressive malignant neoplasm of the soft tissue or bone. "Altogether, these results show that SOX2, ALDH1A1 and ALDH1A3 expression, together with their associated ALDEFLUOR activities are progressively enhanced in CSC subpopulations during sarcoma progression toward more aggressive phenotypes." (PMID 27292183, 2016). "These striking results suggest that ALDH1A1 may play different roles in the tumorigenesis and stemness of sarcomas than were commonly reported in carcinomas." (PMID 31941033, 2020). "We show here that it is in fact the downregulation (not upregulation) of ALDH1A1 gene expression that is associated with aggressive tumors and strongly predicts (p < 0.0001) poor prognosis among various sarcomas." (PMID 31941033, 2020). "Lower levels of sarcoma CSC markers SOX2, NANOG, ALDH1A1, ABCB1 and ABCC1 were observed in silenced cells in 2D and in CSC-enriched cultures (single-cell and 3D/spheroid)." (PMID 35864381, 2022). "In a liposarcoma xenograft model, a small population of ALDH1A1- and CD133-expressing cells had inducible cancer stem cell potential, and high ALDH1 activity in sarcoma cell lines was characterized by a significantly increased proliferation rate." (PMID 24345474, 2013). "Besides, CSC and drug-resistance related genes in sarcoma such as SOX2, NANOG, ALDH1A1, ABCB1 and ABCC1 were down-regulated in 2D, as well as in CSC-enriched cultures (colony-forming and 3D/ spheroid)." (PMID 35864381, 2022).
esophageal cancer (11 papers, 2012 to 2024). A primary or metastatic malignant neoplasm involving the esophagus. "Although the impact of ADH1B on esophageal cancer risk is well documented, this is the first identification of the genetic contribution of the other four (GCKR, KLB, ALDH1A1, and ALDH2) to esophageal cancer risk." (PMID 38277453, 2024). "Of these, four (GCKR, ADH1B, ALDH1A1, and ALDH2) were found to potentially interact with rs671 on the risk of esophageal cancer." (PMID 38277453, 2024). "Of the discovered loci, four (GCKR, ADH1B, ALDH1A1, and ALDH2) were suggested to interact with rs671 in the risk of esophageal cancer, a representative alcohol-related disease." (PMID 38277453, 2024). "The interaction analysis further highlighted the potential combined effect of GCKR, ADH1B, ALDH1A1, and ALDH2 with rs671 GA toward increased (GCKR, ADH1B, and ALDH1A1) or decreased (ALDH2) risk of esophageal cancer and thereby carries important implications for personalized prevention." (PMID 38277453, 2024). "The rs671 genotype stratification revealed that contributions to esophageal cancer risk from GCKR, ALDH1A1, and ALDH2 might be observable exclusively among heterozygotes." (PMID 38277453, 2024). "Although immunohistochemistry with a specific antibody against ALDH1A1 has been used to identify both somatic stem cells and cancer stem cells, ALDH1A1 expression has not been evaluated in human esophageal cancer." (PMID 23095512, 2012).
thyroid cancer (11 papers, 2014 to 2025). "Expression of ALDH1A1/B1 was significantly decreased based on individual cancer stages and tumor histology, and high levels of ALDH1A1/B1 were associated with poor overall survival in thyroid cancer patients." (PMID 35280765, 2022). "To determine if ALDH1A1/A3/B1 is associated with tumor progression and clinical outcome of thyroid cancer, we assessed the correlation between the expression of ALDH1A1/A3/B1 and the pathological stage of the patients." (PMID 35280765, 2022). "In conclusion, we have revealed the aberrant expressions of ALDH1A1/B1 in thyroid cancer tissues that were significantly correlated with the OS of patients and with the pathological stage." (PMID 35280765, 2022). "Although all six ALDH1 members have been reported to be intracellularly involved in various biological processes, ALDH1A1/A3/B1 were the highly expressed genes in thyroid cancer tissues in this study." (PMID 35280765, 2022). "Aberrantly elevated ALDH1A1/B1 levels in cancer tissues were negatively correlated with OS in thyroid cancer patients." (PMID 35280765, 2022). "Taken together, we identified that ALDH1A1/A3/B1 in thyroid cancer patients were significantly correlated with OS in male patients, supporting the possible prognostic value of these enzymes particularly for male patients with thyroid cancer." (PMID 35280765, 2022). "Here, we showed that ALDH1A1/B1 expressions were significantly decreased in thyroid cancer patients, but ALDH1A3 was elevated." (PMID 35280765, 2022). "As the expressions of ALDH1A1/A3/B1 were relatively high in thyroid cancer tissues, we assessed the level of ALDH1A1/A3/B1 in thyroid tumors and normal tissues." (PMID 35280765, 2022). "We demonstrated that the levels of ALDH1A1/B1 had been significantly decreased in thyroid cancer patients." (PMID 35280765, 2022). "We have observed a decreased expression of ALDH1A1/B1 in thyroid cancer tissues, which was correlated with poor survival of patients." (PMID 35280765, 2022). "The correlation between ALDH1A1 expression levels and thyroid cancer prognosis was analyzed with the Kaplan-Meier method." (PMID 24485040, 2014). "Notably, genes such as B4GALT1, ALDH1A1, NDUFV2, and ACO1 had mutations in 6% of samples, making them frequent mutational targets in thyroid cancer." (PMID 40861812, 2025). "Collectively, these results indicate that ALDH1A1/A3/B1 may influence thyroid cancer via metabolism and interaction with various enzymes and transcription factors." (PMID 35280765, 2022). "Thus, we aimed to verify the levels of ALDH1A1/B1 in thyroid cancer cell lines and thyroid cancer tissues in vitro." (PMID 35280765, 2022). "However, future studies are required to validate our findings and promote the clinical utility of ALDH1A1/B1 in thyroid cancer treatment." (PMID 35280765, 2022). "Furthermore, immunohistochemical results verified that ALDH1A1, ALDH1A3, and ALDH1B1 were highly expressed in thyroid cancer at the protein level, suggesting the role of ALDH1A1/A3/B1 in thyroid cancer development." (PMID 35280765, 2022). "Furthermore, to study the role of ALDH1A1/A3/B1 in thyroid cancer, we constructed protein–protein interaction networks by using the tool of inBio Discover." (PMID 35280765, 2022). "Overall, our data provide motivation to better understand the tumor promotion and immune inhibition role of ALDH1A1/B1 in thyroid cancer patients, suggesting that ALDH1A1/B1 might serve as potential prognostic biomarkers for thyroid cancer treatment." (PMID 35280765, 2022). "Thus, ALDH1A1/B1 are potential biomarkers for thyroid cancer and might be valuable therapeutic targets for diagnosis and therapy." (PMID 35280765, 2022). "Therefore, we determined the expressions of ALDH1A1/A3/B1 in thyroid cancer tissues." (PMID 35280765, 2022). "In addition, we also detected a decreased expression of ALDH1A1/B1 in thyroid cancer tissues." (PMID 35280765, 2022).
thyroid cancer (continued). "Flow cytometry was employed to assess the expression of putative thyroid cancer stem cell markers CD44 and CD133, as well as ALDH1A1, in MTC cell lines." (PMID 39595993, 2024). "We observed that the regulatory functions of ALDH1A1 and ALDH1B1 in thyroid cancer were involved in poor outcome in patients and inhibition of TILs." (PMID 35280765, 2022). "Our results showed that the transcriptional levels of ALDH1A1 and ALDH1B1 significantly decreased in thyroid cancer tissues, whereas that of ALDH1A3 increased." (PMID 35280765, 2022). "MRNA expressions of ALDH1A1 and ALDH1B1 significantly decreased in thyroid cancer tissues compared to that in normal groups based on individual cancer stages, gender, tumor histology, and nodal metastasis." (PMID 35280765, 2022). "Expression levels of ALDH1A1, CD44, OCT3/4, and ABCG2 gene were 9.78, 7.02, 9.75, and 7.96 times more in stage III thyroid carcinoma than that in benign thyroid mass, respectively." (PMID 31341476, 2019). "Thus, ALDH1A1 may be a new therapeutic target with relevance in thyroid carcinoma." (PMID 24485040, 2014). "Similarly, ALDH1A1, alongside other aldehyde dehydrogenase family members such as ALDH4A1 and ALDH3A2, underscores the role of metabolic dysregulation in thyroid cancer progression." (PMID 40861812, 2025). "Interestingly, the expressions of ALDH1A1 and ALDH1B1 were higher in the normal thyroid tissues and decreased in the thyroid cancer tissues." (PMID 35280765, 2022). "Of note, our results showed a negative correlation between ALDH1A1/B1 and several chemokines/receptors in thyroid cancer tissues." (PMID 35280765, 2022). "Our results showed that changes in the expression level of ALDH1A1/A3 had no influence over the OS of female patients with thyroid cancer; however, increased mRNA level of ALDH1A1 impaired OS in male patients with thyroid cancer." (PMID 35280765, 2022). "Also ALDH1A1 positivity rates in normal/cancerous thyroid tissues/cells and expression levels of CD133, SSEA-1, and CD24 in thyroid cancer cells varied among different studies." (PMID 26973599, 2016). "However, the prognosis and clinical significance of ALDH1A1 is not very clear, particularly in certain histological types of thyroid cancer." (PMID 24485040, 2014). "Using the TISIDB database, we demonstrated that ALDH1A1/A3/B1 had significant negative correlations with immune-stimulating genes, such as CD276, TMEM173, TNFSF9, CD70, TNFRSF25, and CD40 in thyroid cancer." (PMID 35280765, 2022).
cholangiocarcinoma (10 papers, 2016 to 2026). A carcinoma that arises from the intrahepatic biliary tree (intrahepatic cholangiocarcinoma) or from the junction, or adjacent to the junction, of the right and left hepatic ducts (hilar cholangiocarcinoma). "Given that intrahepatic cholangiocellular carcinoma falls under the category of rare diseases, resulting in a naturally low patient count, there is a pressing need for further studies to investigate potential gender-specific biological mechanisms underlying ALDH1A1 expression in iCC." (PMID 39744576, 2025). "In this study, the stem cell marker panel (including CD133 and ALDH1A1) was evaluated on 178 cases of cholangiocarcinoma." (PMID 40008905, 2025). "Previous studies have reported that histone acetylation levels regulate ALDH1A1 expression levels via transcription in cholangiocarcinoma." (PMID 33994921, 2021). "And BAF250a deletion in cholangiocarcinoma (CCA) enhances ALDH1A1‐mediated cancer stem cell expansion." (PMID 41578412, 2026). "Therefore, ARID1A may function as a tumor suppressor in cholangiocarcinoma through the transcriptional downregulation of ALDH1A1, along with a decrease in the levels of histone H3K27 acetylation." (PMID 35814382, 2022). "Similarly, in cholangiocarcinoma cells, ARID1A binding to the promoter of ALDH1A1 blocks the transcription of ALDH1A1." (PMID 38229120, 2024).